WDR13 (WD repeat domain 13)
Synonyms: MG21
Tractability: Antibody: its Gene Ontology location is reachable by antibodies, with high confidence. PROTAC: ubiquitination databases record sites on it; its protein half-life has been measured.
Gene: Protein-coding gene on chromosome X (48,589,838 to 48,608,869, forward strand). Ensembl gene ENSG00000101940.
Subcellular location: Nucleus
Subcellular location (Human Protein Atlas): Nucleoplasm; Centriolar satellite; Plasma membrane
Gene Ontology:
Molecular function: promoter-specific chromatin binding
Cellular component: nucleoplasm; nucleus
Homologues: Orthologues: chimpanzee WDR13 (100% identical), macaque WDR13 (99% identical), dog WDR13 (99% identical), pig WDR13 (99% identical), mouse Wdr13 (99% identical), guinea pig WDR13 (99% identical), rat Wdr13 (96% identical), rabbit WDR13 (94% identical), tropical clawed frog wdr13 (83% identical), zebrafish wdr13 (83% identical), Caenorhabditis elegans gid-7 (16% identical). Paralogues in human: WDR26 (24% identical).
Diseases named in the same sentence as WDR13 in open-access papers:
WDR13 is named in the same sentence as 24 diseases in open-access papers, as found by Europe PMC text mining. Sharing a sentence is not in itself a finding about the gene and the disease. The quoted sentences say what the papers report.
Obesity (5 papers, 2012 to 2020). Accumulation of substantial excess body fat. "The present study focusses on Wdr13 knockout female mice as a potential mouse model to study EH condition that also associates with lifestyle related risk factors such as obesity, hyperinsulinemia and elevated estradiol levels." (PMID 32883989, 2020). "Wdr13 deficient male mice (Wdr13-/0) showed age dependant changes in the metabolic parameters, namely; mild obesity and the increased insulin levels." (PMID 29743870, 2018). "In conclusion, we provide evidence that WDR13 deficiency in mice leads to increased pancreatic islet mass, hyperinsulinemia, better glucose clearance and mild obesity." (PMID 22715406, 2012). "Apart from the age dependent obesity and hyperinsulinemia, Wdr13 knockout female mice have elevated plasma estradiol levels." (PMID 32883989, 2020). "Taken together, uterine hyperplasia accompanied by increased estradiol, hyperinsulinemia and obesity in these Wdr13 knockout female mice, makes them a good model to study EH condition." (PMID 32883989, 2020). "Hyperinsulinemia, accompanied by mild obesity in Wdr13 knockout mice appears to be reminiscent of MOR1 and chop knockout mice, where adiposity is enhanced by higher insulin secretion." (PMID 22715406, 2012). "To understand the in vivo role of Wdr13 gene, we have created a mouse strain lacking this gene and show that these mice have higher pancreatic islet mass as a result of higher beta cell proliferation, develop hyperinsulinemia and mild obesity." (PMID 22715406, 2012).
Anxiety (3 papers, 2016 to 2021). Intense feelings of nervousness, tension, or panic often arise in response to interpersonal stresses. "We have shown that Wdr13-/0 mice when subjected to 3 weeks of social isolation stress resulted in a phenotype exhibiting anhedonia, heightened anxiety and heightened behavioral despair." (PMID 29743870, 2018). "We had shown earlier that Wdr13 has a brain specific function with the mutant mice exhibiting mild anxiety, better memory retention and increased expression of synaptic genes." (PMID 29743870, 2018). "Based on existing literature and the pattern of expression of Wdr13 in the brain, we analyzed Wdr13−/0 mice for any altered anxiety or cognitive function (s)." (PMID 27625594, 2016). "Additional studies have shown that the absence of Wdr13 protein predisposes mice to a depression-like phenotype with mild social isolation, anxiety, and chronic stress." (PMID 34946860, 2021). "Interestingly, socially isolated Wdr13-/0 mice also spent increased time in closed arm of Elevated plus maze (t-test; p < 0.05) indicating hightened anxiety." (PMID 29743870, 2018). "Thus, the absence of Wdr13 predisposed these mice to hightened anxiety and behavioral despair as measured by OFT and FST upon subjection to 3 weeks social isolation." (PMID 29743870, 2018). "We earlier reported that the male mice lacking the Wdr13 gene (Wdr13-/0) showed mild anxiety, better memory retention, and up-regulation of synaptic proteins in the hippocampus." (PMID 29743870, 2018).
diabetes (3 papers, 2012 to 2020). "Given the higher insulin levels and better glucose clearance in Wdr13 gene deficient mice, we propose that this protein may be a potential candidate drug target for ameliorating impaired glucose metabolism in diabetes." (PMID 22715406, 2012). "It was thus, interesting to see the role of WDR13 in streptozotocin-mediated diabetes in mice, a model for type I diabetes." (PMID 30369599, 2018). "We propose that given the higher random insulin levels and better glucose clearance in Wdr13 knockout mice, this protein may be explored as a potential candidate drug target for ameliorating impaired glucose metabolism in diabetes." (PMID 22715406, 2012). "Previously, we have reported that the absence of WDR13 in diabetic Leprdb/db mice helps in amelioration of fatty liver phenotype along with diabetes and systemic inflammation." (PMID 33292732, 2020).
Hyperinsulinemia (3 papers, 2012 to 2020). An increased concentration of insulin in the blood. "An earlier study from our laboratory has shown that hyperinsulinemia and hypertrophy of the adipose tissue were observed in the Wdr13 knockout male mice at 12 months of age." (PMID 32883989, 2020). "Further, glucose tolerance test results showed a better clearance of glucose in the knockout than in the wildtype mice indicating hyperinsulinemia condition in female Wdr13 knockout mice." (PMID 32883989, 2020).
depression (2 papers, 2016 to 2018). "Considering that this gene is highly conserved, Wdr13 emerges as a candidate to be considered for genetic screening in patients with Major Depressive Disorder." (PMID 29743870, 2018). "Increased levels of GATA1 have been reported in post-mortem samples of clinically depressed individuals and the overexpression of GATA1 led to a phenotype of depression-like-symptoms in rat, which was similar as in the socially isolated Wdr13-/0 mice." (PMID 29743870, 2018). "Indeed, in the socially isolated Wdr13-/0 mice, there was an up-regulation of GATA1 – a transcription factor that negatively regulates synaptic genes and has been associated with Major Depression (MD) in humans." (PMID 29743870, 2018). "Thus, taken together behavioral, anatomical and molecular changes obeserved in the socially isolated Wdr13-/0 mice were reminiscent of Major Depression (MD) in human beings." (PMID 29743870, 2018). "Interestingly, epigenetic analysis in mice models of depression have showed that the repressive chromatin marks on Wdr13 decreased upon stress indicating the possible up-regulation of this gene in response to stress." (PMID 29743870, 2018). "Exhibiting endophenotypes of depression that are responsive to anti-depressants, Wdr13-/0 mice represent a very intriguing model system to study Major Depression- like phenotype and may be useful in pharmacological studies." (PMID 29743870, 2018). "Hence, Gata1 expression might be directly correlated with depression like phenotype of socially isolated Wdr13-/0 mice." (PMID 29743870, 2018). "Finally, our observations from this work – WDR13 is responsive to stress and the absence of it predisposes mice to symptoms of depression, resonates with the findings from our other experiments." (PMID 29743870, 2018). "Our results predicted a possible role of WDR13 in regulation of GATA1 and it appeared likely that the absence of Wdr13 predisposed mutant mice to Major Depression-like phenotype when subjected to social isolation stress through this master regulator." (PMID 29743870, 2018).
hyperglycaemia (2 papers, 2018 to 2020). "We found that the Wdr13-/0 mice demonstrated better recovery from hyperglycaemia second week onwards, had better insulin levels and gained more body weight than the Wdr13+/0 mice." (PMID 30369599, 2018). "WDR13 deletion in Leprdb/db mice improved adipose and pancreatic function which resulted in reduced dyslipidemia and hyperglycemia, two systemic factors contributing towards hepatosteatosis, leading to reduced serum triglycerol and free-fatty acids hence ameliorating the fatty liver phenotype." (PMID 33292732, 2020).
colitis (1 paper, 2017). Inflammation of the colon. "In the present study, we used AOM/DSS to induce colitis-mediated colorectal tumor after establishing expression of Wdr13 gene in colon." (PMID 28222755, 2017). "To rule out the possibility of resistance to DSS-induced ulceration and colitis in Wdr13-/0 mice, we analysed colon histology of Wdr13+/0 and Wdr13-/0 mice during the recovery period." (PMID 28222755, 2017). "To understand the mechanism of protection from colitis-induced colon tumor in Wdr13-/0 mice, we measured the proliferative and apoptotic index of control, and AOM/DSS-treated Wdr13+/0 and Wdr13-/0 mice." (PMID 28222755, 2017). "The primary reason for the protection against colitis-induced colorectal tumor in Wdr13 knockout mice is likely to be the resultant ulceration and the increased apoptosis." (PMID 28222755, 2017). "However, after AOM/DSS-induced colitis, there was a significant increase in the number of apoptotic cells in Wdr13-/0 mice as compared to Wdr13+/0 mice." (PMID 28222755, 2017). "Interestingly, after DSS treatment, Wdr13-/0 mice showed more ulceration than wild-type littermates, which may explain the reduced incidence of colitis-induced colorectal tumor in these mice." (PMID 28222755, 2017). "The lack of Wdr13 gene conferred protection to a large extent against colitis-induced colorectal tumor in mice through reduced expression of AP1 target genes." (PMID 28222755, 2017). "Mice lacking Wdr13 gene showed reduced expression of AP1 target genes and protection from colitis-induced colorectal tumors." (PMID 28222755, 2017).
colon cancer (1 paper, 2017). "Further, we have used human colon cancer cell lines, HT29 and COLO205, and mouse primary embryonic fibroblast to understand the molecular mechanism of WDR13 action." (PMID 28222755, 2017).
colorectal tumors (1 paper, 2017). "In the present study, we have shown that Wdr13 knockout mice were protected to a large extent from AOM/DSS-induced colorectal tumor." (PMID 28222755, 2017). "The expression of Wdr13 in colon along with the well-known function of c-Jun in the development of colorectal tumor encouraged us to analyze the phenotype of Wdr13 knockout mice." (PMID 28222755, 2017). "However, there was no activation of AP1 target genes, and protection from AOM/DSS-induced colorectal tumor in Wdr13-/0 mice." (PMID 28222755, 2017). "We show that the lack of Wdr13 gene protects mice from AOM/DSS-induced colorectal tumors." (PMID 28222755, 2017). "Given the presence of this protein in colon, we used AOM/DSS (Mr- 40,000) to induce colorectal tumor in order to know whether the lack of Wdr13 gene affected tumor progression." (PMID 28222755, 2017).
endometrial adenocarcinoma (1 paper, 2020). "Wdr13 knockout mice is a whole body knockout and hence to undermine the systemic effects of the same, in vitro studies were conducted in Ishikawa cells (human endometrial adenocarcinoma cell line)." (PMID 32883989, 2020).
hypertriglyceridemia (1 paper, 2020). A laboratory test result indicating elevated triglyceride concentration in the blood. "Also the Wdr13−/0 mice exhibit liver hypertriglyceridemia due to de novo lipogenesis, during the regeneration phase after CCl4 toxicity." (PMID 33292732, 2020). "We want to highlight the fact that absence of WDR13 per se does not induce de novo lipogenesis and fatty liver but when these mutant mice are subjected to CCl4 stress, liver hypertriglyceridemia is observed via upregulation of PPAR pathway." (PMID 33292732, 2020). "Taken together, these results indicated that the observed hepatic hypertriglyceridemia was more likely due to de novo lipogenesis in Wdr13−/0 mice rather than due to systemic absence of Wdr13 gene in tissues other than the liver." (PMID 33292732, 2020). "Activation of PPAR pathway is also observed in Wdr13−/0 primary hepatocytes when treated with CCl4, which confirms that hypertriglyceridaemia seen in vivo is indeed due to the liver-specific absence of WDR13." (PMID 33292732, 2020). "The circulating triglycerides and cholesterol levels in Wdr13−/0 mice were also found similar to that in Wdr13+/0 mice, suggesting that the observed liver hypertriglyceridemia is indeed due to de novo lipogenesis and not because of systemic factors." (PMID 33292732, 2020).
Intellectual disability (1 paper, 2021). "Our study found a loss-of-function variant of the WDR13 gene in a male patient with an intellectual disability whose family history indicates X-linked inheritance." (PMID 34946860, 2021). "Little is known about the role of the WDR13 protein in the development of intellectual disability." (PMID 34946860, 2021). "Therefore, it is necessary to conduct detailed research that would allow for a better understanding of the process of intellectual disability development related to the WDR13 gene." (PMID 34946860, 2021).
neuroblastoma (1 paper, 2018). Neuroblastoma (NB) is the most common solid, extracranial childhood tumor. "Further, overexpression of WDR13 in IMR-32 human neuroblastoma cell line decreased the transcript levels of Gata1 by 1.5-fold (Mann–Whitney; p < 0.05)." (PMID 29743870, 2018).
schizophrenia (1 paper, 2016). A major psychotic disorder characterized by abnormalities in the perception or expression of reality. "Hence, it should be investigated whether absence of Wdr13 leads to hallucinogenic or schizophrenia like effect in mice with increasing age." (PMID 27625594, 2016).
steatosis (1 paper, 2020). Increased lipid within the cytoplasm of cells. "Besides hepatotoxin stress, this study also reveals that the absence of WDR13 per se renders the liver susceptible to steatosis owing to the upregulated PPARγ and p38α in the control (vehicle treated) Wdr13−/0 mice." (PMID 33292732, 2020).
type I diabetes (1 paper, 2018). "In the light of above data it was interesting to study the role of WDR13 in β-cell proliferation in the type I diabetes mice model, for which we used multiple low-doses STZ-treatment to Wdr13-/0 mice and their wild type littermates (Wdr13+/0)." (PMID 30369599, 2018).
type II diabetes (1 paper, 2018). "Also, amelioration of the diabetic phenotype on introgression of Wdr13-null (Wdr13-/0) mutation in genetically diabetic mice (Leprdb/db) [type II diabetes] was observed." (PMID 30369599, 2018).
X-linked intellectual disability (1 paper, 2021). An X-linked intellectual deficiency in which not enough information is known, reported or published to indicate whether a gene causes non-syndromic or syndromic presentations. "WDR13 is a poorly characterized gene previously proposed as a candidate gene for X-linked intellectual disability." (PMID 34946860, 2021).
cancer (1 paper, 2017). A tumor composed of atypical neoplastic, often pleomorphic cells that invade other tissues. "Since our in-vitro experiments showed that WDR13 regulates AP1 target genes, and as the AOM/DSS-cancer model is known to have higher expression of AP1 target genes, we studied the expression of these genes in colon." (PMID 28222755, 2017).
metabolic disorders (1 paper, 2020). "Thus, the genetic loss of Wdr13 in these mice led to mimicking of the human EH associated metabolic disorders making Wdr13 knockout female mice a potential animal model to study human endometrial hyperplasia." (PMID 32883989, 2020).
tumor (1 paper, 2017). "Since the WDR13 protein isoforms are present in various tissues and it is a negative regulator of beta cell proliferation, we observed these knockout mice till one year of age for any tumor progression." (PMID 28222755, 2017).
WDR13 also shares sentences with these, for which no sentence is quoted: colon tumor (1 paper); dyslipidemia (1); psychiatric disorder (1).